FLOT2 (flotillin 2)
Diseases named in the same sentence as FLOT2 in open-access papers (continued):
Sharing a sentence is not in itself a finding about the gene and the disease.
melanoma (15 papers, 2009 to 2024). A malignant, usually aggressive tumor composed of atypical, neoplastic melanocytes. "Over-expression of Flot-2 has been reported to be associated with human melanoma progression and lymph node metastasis." (PMID 25014228, 2014). "The same group also showed that flotillin-2 expression is associated with Breslow depth and lymph node metastasis in melanoma." (PMID 24709906, 2014). "FLOT2 overexpression has been reported to be associated with human melanoma progression and the development of metastasis in human head and neck squamous cell carcinomas." (PMID 23945257, 2013). "FLOT2 might promote PAR-1-induced constitutive signaling through the BRAF-MAPK-ERK pathway implicated in melanoma progression." (PMID 23945257, 2013). "Indeed high flotillin-2 expression has been shown to be associated with lymph node metastasis and melanoma progression and expression of flotillin-1 and -2 was induced during G-CSF induced myeloid progenitor cell proliferation and granulocyte differentiation." (PMID 20027317, 2009). "Total splenic IFN-γ production to melanoma TRP-2 peptide stimulation was also elevated in B16F10 tumor–bearing Flot2–/– mice compared with their Flot2+/+ counterparts, indicating an enhanced response to tumor antigen." (PMID 39499901, 2024). "Another mode of action for MIR4435-2HG is competitive binding to miR-802, which leads to increased expression of FLOT2 and promotes the progression of melanoma." (PMID 37998733, 2023). "As we expected, the mRNA and protein levels of FLOT2 were markedly raised in melanoma tissues relative to normal tissues." (PMID 32183822, 2020). "The analysis of FLOT2 mRNA and protein levels in melanoma cells and HEMn cells showed that the mRNA and protein levels of FLOT2 were notably elevated in A2058 and A375 cells compared to HEMn cells." (PMID 32183822, 2020). "Next, we determined the mRNA and protein levels of FLOT2 in melanoma tissues and normal skin tissues." (PMID 32183822, 2020). "All these data suggested that miR-143-3p negatively modulated FLOT2 expression by interacting with FLOT2 in melanoma cells." (PMID 32183822, 2020). "In the presented research, the expression patterns of circ-FOXM1, miR-143-3p, and FLOT2 in melanoma were determined." (PMID 32183822, 2020). "Herein, FLOT2 elevation abrogated the influences of miR-143-3p on cell growth, metastasis, and glycolysis in melanoma, indicating that miR-143-3p altered melanoma cell development via interacting with FLOT2." (PMID 32183822, 2020). "Earlier findings have suggested that increased flotillin-2 expression correlates with a high metastatic potential of melanoma cells." (PMID 29642469, 2018). "And over-expression of Flot-2 in SB2 melanoma cells facilitated the transformation of their phenotype from non-tumorigenic, non-metastatic to highly tumorigenic and metastatic in the nude mouse xenograft model." (PMID 25014228, 2014). "Consequently, this results in a rise in the level of expression of flotillin-2 (FLOT2), a protein associated with lipid rafts, consequently enhancing the malignant actions of melanoma cells." (PMID 37998733, 2023). "We found that miR-195-5p overexpression in BRAF-mutated melanoma cells causes an increase in the expression levels of some EVs biogenesis-related genes like RAB27b, RAB31, and/or FLOT2, which was accompanied by a consequent increase in CD63 and CD9 positive EVs secretion." (PMID 37174717, 2023). "Its overexpression represses proliferation and metastasis in melanoma cells via targeting FLOT2." (PMID 33968718, 2021). "Circ-FOXM1 facilitated the development of melanoma by upregulating FLOT2 through miR-143-3p." (PMID 32183822, 2020). "Moreover, FLOT2 was a target gene of miR-143-3p and FLOT2 overexpression rescued the inhibitory effect of miR-143-3p on melanoma progression." (PMID 32183822, 2020).
melanoma (continued). "Our data provided a novel regulatory network circ-FOXM1/miR-143-3p/FLOT2 axis in melanoma progression and might have a crucial implication for melanoma treatment." (PMID 32183822, 2020). "Furthermore, FLOT2 expression was negatively correlated with miR-143-3p expression in melanoma tissues." (PMID 32183822, 2020). "All these outcomes suggested that miR-143-3p could suppress melanoma cell progression by targeting FLOT2." (PMID 32183822, 2020). "Moreover, the exogenous flotillin-2 expression in melanoma cells leads to the acquisition of metastasizing phenotype." (PMID 24533441, 2014). "Similarly, flotillin-2 is upregulated in melanoma and in metastatic nasopharyngeal carcinoma cells." (PMID 23029064, 2012). "As above for Flot2–/– mice, Flot2CD4 mice were evaluated in the B16F10 melanoma and MC38 colon adenocarcinoma models." (PMID 39499901, 2024). "In summary, circ-FOXM1 was upregulated in melanoma, and circ-FOXM1 contributed to melanoma cell proliferation, motility, and glycolysis and repressed apoptosis by upregulating FLOT2 via targeting miR-143-3p." (PMID 32183822, 2020). "Flotillin 2 (FLOT2) has been proved to play its tumorigenic role in diverse human cancers, including melanoma." (PMID 32183822, 2020). "Furthermore, Flot2–/– mice exhibited an increased frequency of CD4+ and CD8+ tumor-infiltrating lymphocytes (TILs) in the B16F10 melanoma model, specifically including Ki67+ proliferating effector CD4+ and CD8+ cells." (PMID 39499901, 2024). "Xenograft experiments revealed that FLOT2 overexpression facilitated the transformation of the non-metastatic melanoma cell line (SB2) into a highly tumorigenic metastatic cell line." (PMID 23945257, 2013). "Overexpression of flotillin-2 in non-tumorigenic melanoma cells results in melanoma progression and formation of metastases." (PMID 23029064, 2012). "However, whether miR-143-3p can target FLOT2 to participate in the development of melanoma has not been unraveled." (PMID 32183822, 2020).
gastric cancer (13 papers, 2013 to 2025). A primary or metastatic malignant neoplasm involving the stomach. "Similar to Wnt3, Flot2 is linked to tumour development and proliferation, and its expression is increased in gastric cancer (GC)." (PMID 36040316, 2022). "In gastric cancer, flotillin-2 levels show a correlation with Her2 expression and are associated with poor prognosis, whereas in head and neck cancer, flotillin-2 overexpression shows a strong predictive value for the development of metastases." (PMID 24304721, 2013). "Recently, siRNA-mediated Flot2 downregulation was reported to inhibit cell proliferation and invasion in gastric carcinoma, however, the underlying molecular mechanism of Flot2 in cell invasion of GC is largely unknown." (PMID 26576674, 2015). "α3NaK was localized in the cytoplasm of primary gastric cancer cells, whereas in CCCs, α3NaK was colocalized with flotillin-2, a marker for PM." (PMID 40350473, 2025). "miR-449a was found to target Fos and Met in hepatocellular carcinoma and Flot2 in gastric cancer which was found to reduce features of EMT in these cells." (PMID 35879960, 2022). "Together with the Wnt co-receptor and cytoneme initiator Ror2, Flot2 determines the number and length of Wnt3 cytonemes in gastric cancer." (PMID 36040316, 2022). "Flotillin-2 is over-expressed and promotes filopodia formation and elongation in gastric cancer cells." (PMID 36040316, 2022). "Flotillin-2 is is required for TGFβ-induced EMT in gastric cancer cells since downregulation of flotillin-2 reduced the expression of the EMT markers vimentin and N-cadherin." (PMID 33450869, 2021). "In summary, we demonstrated the important role of miR-449a mediated Flot2 suppression that subsequently disarranged TGF-β induced epithelial mesenchymal transition within gastric cancers, thus providing a potential therapeutic target in gastric cancer therapy." (PMID 26576674, 2015). "Furthermore, we identify the membrane-bound scaffolding protein Flotillin-2 (Flot2), frequently overexpressed in gastric cancer, as a modulator of these cytonemes." (PMID 36040316, 2022). "Consequently, Flot2 function correlates positively with colony formation, suggesting that Flot2-dependent Wnt3 cytonemes are essential in promoting proliferation and activity of gastric cancer stem cells." (PMID 36040316, 2022). "However, the underlying molecular mechanism of Flot2 in gastric cancer (GC) is largely unknown." (PMID 26576674, 2015). "FLOT2 is necessary for TGF-β1 and induced epithelial-mesenchymal transition (EMT) in gastric cancer." (PMID 34059086, 2021). "We next assayed the Flot2 expression levels in normal human gastric epithelial cells GES-1 and gastric cancer cell lines (SGC-7901, NCI-N87 and MGC-803) using qRT-PCR and western blot assay." (PMID 26576674, 2015). "Importantly, recent researches have suggested that the flotillin 2 protein expression is significantly correlated with cancer progression and poor prognosis in gastric carcinomas, probably due to its role in the regulation of cell proliferation, migration, and invasion in gastric carcinoma cells." (PMID 25948494, 2015). "Recent data have shown that in gastric tumors, flotillin-2 expression correlates with HER2/ErbB2 levels and flotillin-2 knockdown in a gastric cancer cell line results in reduced HER2 expression." (PMID 24304721, 2013). "Interestingly, miR-449a has been shown to target Flot2 and regulate EMT, thereby inhibiting gastric cancer invasion." (PMID 31345231, 2019). "Flot2, a highly conserved protein of the SPFH domain containing proteins family, has recently been identified as oncogene to be involved in the tumorigenesis and metastasis of several cancers including gastric cancer." (PMID 26576674, 2015).
nasopharyngeal carcinoma (12 papers, 2014 to 2025). A carcinoma arising from the nasopharyngeal epithelium. "Previous studies showed that Flot2 is an indispensable member for TGF-β signaling in nasopharyngeal carcinoma." (PMID 26576674, 2015). "It was recently reported that Flot2 is an indispensable member for TGF-β signaling in nasopharyngeal carcinoma." (PMID 26576674, 2015). "TBL1X could reestablish the functional changes of nasopharyngeal carcinoma cells by Flot2 alteration." (PMID 39390002, 2024). "TBL1X and Flot2 have the same direction of regulation in nasopharyngeal carcinoma." (PMID 39390002, 2024). "We previously reported that expression of Flotillin 2 (Flot-2), a protein isolated from caveolae/lipid raft domains, increased significantly in nasopharyngeal carcinoma (NPC) compared with normal tissues." (PMID 26161893, 2015). "Similar signaling pathways have been observed in tumor cells, where FLOT2 upregulates CD109 by stabilizing the expression of STAT3, inhibiting the TGF-β signaling pathway and promoting the development of nasopharyngeal carcinoma." (PMID 41327642, 2025). "However, the role of the lipid raft protein flotillin-2 (Flot-2) in nasopharyngeal carcinoma (NPC) remains to be comprehensively characterized." (PMID 26206082, 2015). "Therefore, we intended to find out the relationship between Flot2 and TGF-β in the process of nasopharyngeal carcinoma (NPC) metastasis." (PMID 25909165, 2015). "Previously, we elucidated the function of flotilin-2 (FLOT2) and branched-chain amino acid transaminase 1(BCAT1) in nasopharyngeal carcinoma (NPC)." (PMID 33744853, 2021).
glioma (6 papers, 2020 to 2025). A benign or malignant brain and spinal cord tumor that arises from glial cells (astrocytes, oligodendrocytes, ependymal cells). "The inhibition of FLOT2 expression subsequently suppressed glioma progression via the FLOT2/AKT1 signaling pathway." (PMID 41264121, 2025). "The researchers found that miR-124-3p targeted the flotillin 2 (FLOT2) gene in gliomas, suppressing FLOT2 expression and affecting the AKT1 pathway." (PMID 39450275, 2024). "The study also demonstrated that NSC-EXOs loaded with miR-124-3p effectively inhibited glioma growth by activating the EXO-miR-124-3p/FLOT2/AKT1 pathway." (PMID 39450275, 2024). "For example, the oncogene FLOT2, which is a known target of miR-449, was recently shown to be greatly upregulated in glioma tissues and cell lines, and its expression level was associated with tumor stage and size." (PMID 36425564, 2022). "In a study, miR-449 could bind directly to the 3’UTR of FLOT2 and regulate FLOT2 expression in glioma cells." (PMID 36425564, 2022).
lymph node metastasis (5 papers, 2009 to 2020). "Also, higher expression of Flot-2 is associated with the lymph node metastasis and clinical stages in NPC." (PMID 25014228, 2014). "A recent study also revealed the correlation between Flot-2 expression and lymph node metastasis in NPC patients." (PMID 26206082, 2015). "We further analyzed the associations between expression of Flot-2 protein and NPC clinicopathological features including patients' age, gender, clinical stages, histological type, lymph node metastasis, and survival status by univariate Chi-Square Test." (PMID 25014228, 2014). "Multivariate analysis proved that Flot-2 positive expression was an independent predicted factor for lymph node metastasis in NPC excluding clinical stages." (PMID 25014228, 2014). "The positive predictive value indicates the possibility of diagnosis of NPC with lymph node metastasis when the expression of Flot-2 protein is positive." (PMID 25014228, 2014). "In this study, Flot-2 protein was found to show a higher sensitivity (93%) and agreement rate (75.4%) for identifying lymph node metastasis in NPC." (PMID 25014228, 2014). "The expression of Flot-2 was proved to be the independent predicted factor for lymph node metastasis by multivariate analysis." (PMID 25014228, 2014). "Also, Flot-2 is an independent prognostic factor and a potential novel biomarker for lymph node metastasis in gastric cancer." (PMID 25014228, 2014). "Moreover, multivariate analysis confirmed that increased expression of Flot-2 protein might be an independent predictive factor for lymph node metastasis in NPC." (PMID 25014228, 2014). "By analyzing the association between expression of Flot-2 protein and clinicopathological characteristics of NPC, we first report that high expression of Flot-2 protein was the independent predicted factor for lymph node metastasis in NPC excluding clinical stages." (PMID 25014228, 2014). "To investigate the clinical outcome due to the over-expression of Flot-2 and EGFR in cancer tissues, we next investigated clinicopathological features of NSCLC including age, gender, clinical stages, lymph node metastasis (LNM) status, and pathological differentiation in univariate chi-square test." (PMID 26161893, 2015). "Consistently, increased Flot-2 expression was also reported in NPC patients with lymph node metastasis compared with patients without lymph node metastasis." (PMID 26161893, 2015). "The positive percentage of Flot-2 protein expression in NPC patients with lymph node metastasis was significantly higher than those without lymph node metastasis." (PMID 25014228, 2014). "The negative predictive value indicates the possibility of diagnosis of NPC without lymph node metastasis when the expression of Flot-2 protein is negative." (PMID 25014228, 2014). "In this study, our results indicated that expression of Flot-2 protein in NPC with lymph node metastasis was significant higher than those without lymph node metastasis by univariate analysis." (PMID 25014228, 2014). "Furthermore, there was statistically significant difference between the positive expression of Flot-2 protein in the NPC with lymph node metastasis and those without lymph node metastasis (P = 0.008)." (PMID 25014228, 2014). "The sensitivity evaluates the ability of Flot-2 protein in diagnosis correctly the lymph node metastasis of NPC, and the specificity evaluates its ability about judgment in NPC patients without lymph node metastasis." (PMID 25014228, 2014).
hepatocellular carcinoma (4 papers, 2015 to 2022). A malignant tumor that arises from hepatocytes. "Likewise, overexpression of FLOT2 was shown to result in epithelial-mesenchymal transition of tumor cells and, thereby, metastasis in hepatocellular carcinoma and overexpression of PPIF was reported to be a poor prognostic sign in endometrial cancer." (PMID 36506940, 2022). "For example, in hepatocellular carcinoma (HCC), FLOT-2 was found to promote metastatic progression by controlling cell cycle progression and inducing the epithelial-mesenchymal transition (EMT) via MEK/Raf/ERK signaling activity." (PMID 34803501, 2021).
Insulin resistance (4 papers, 2019 to 2025). Increased resistance towards insulin, that is, diminished effectiveness of insulin in reducing blood glucose levels. "FLOT2 is associated with insulin resistance and was found to be upregulated in granulosa cells from PCOS patients." (PMID 35002524, 2022). "Another study suggested that FTO could also contribute to insulin resistance in PCOS by removing the m6A modification from the membrane-associated protein FLOT2 (Flotillin-2) mRNA." (PMID 39904996, 2025).
lung adenocarcinoma (4 papers, 2015 to 2023). A carcinoma that arises from the lung and is characterized by the presence of malignant glandular epithelial cells. "Additionally, as a direct target of miR-133, FLOT2 was regulated via Akt signaling and played pro-metastatic role in lung adenocarcinoma cell." (PMID 30820716, 2019).
breast tumor (3 papers, 2013 to 2019). "Taken together, these observations show that high levels of FLOT2 expression were associated with the clinical development of primary breast tumors." (PMID 23945257, 2013). "Earlier studies have already shown that flotillin-2 is up-regulated in ErbB2 overexpressing breast tumor biopsies." (PMID 24709906, 2014). "Interestingly, we also found an increase in the expression of both flotillin-1 and flotillin-2 in breast tumor cells after treatment." (PMID 31562347, 2019).
cervical carcinoma (2 papers, 2015 to 2025). A carcinoma arising from either the exocervical squamous epithelium or the endocervical glandular epithelium. "However, in cervical cancer cells, p-AKT has been associated with increased expression of flotillin 2 encoded by the gene FLOT2." (PMID 40429638, 2025).
diabetic kidney disease (2 papers, 2023 to 2025). Progressive kidney disorder caused by vascular damage to the glomerular capillaries, in patients with diabetes mellitus. "While mutations in Flot2 have not been directly implicated in monogenic nephrotic syndromes, altered expression of Flot2 has been reported in kidney diseases such as FSGS and diabetic nephropathy." (PMID 41368354, 2025).
dilated cardiomyopathy (2 papers, 2016 to 2022). Cardiomyopathy which is characterized by dilation and contractile dysfunction of the left and right ventricles. "Notably, expression levels of Flotillin-2 were significantly increased in cardiac intercalated disk fractions from both Dilated Cardiomyopathy (DCM) and Arrhythmogenic Right Ventricular Cardiomyopathy (ARVC) patients." (PMID 34929167, 2022). "Therefore we investigated the localization of FLOT2 further in left ventricular tissue samples obtained from two dilated cardiomyopathy patients (DCM)." (PMID 27148881, 2016).
esophageal squamous cell carcinoma (2 papers, 2013 to 2015). Esophageal squamous cell carcinoma (ESCC) is a type of esophageal carcinoma (EC) that can affect any part of the esophagus, but is usually located in the upper or middle third. "Recently, miR-138 was reported to be down-regulated in esophageal squamous cell carcinoma (ESCC) and the markers of lipid rafts FLOT1, FLOT2 and caveolin-1 were identified as its targets, and NF-kappaB was activated." (PMID 24204780, 2013).